YY1 (YY1 transcription factor)
Diseases named in the same sentence as YY1 in open-access papers (continued):
Sharing a sentence is not in itself a finding about the gene and the disease.
tumor (continued). "The clinical data analysis with various public databases and CRC tumor tissues confirmed the high expression levels of USP7 and YY1 in CRC, along with a positive correlation between them." (PMID 38769122, 2024). "Prolonged T cell activation upregulates both YY1 and EZH2 proteins that repress IL-2, a cytokine involved in their capability to kill tumor cells." (PMID 38339244, 2024). "The expression of TF-protein YY1 (a regulator of CXCL8, ADH1C, CEMIP, ZG16, and CLCA4) contributes to tumor growth differs in different cancers." (PMID 36991484, 2023). "Further studies also revealed that YY1 represses the TRAIL receptor DR5 and its inhibition by NO or by the upregulation of RKIP resulted in the sensitization of TRAIL-resistant tumor cells to TRAIL apoptosis." (PMID 37205308, 2023). "YY1 is a multipurpose TF protein that can stimulate or suppress gene expression and plays a significant role in CRC tumor growth." (PMID 36900162, 2023). "Overall, our findings underscore the significant role of the interplay between YY1 and PEBP1 in cancer progression, influencing genomic changes, tumor immunity, or the tumor microenvironment." (PMID 37894300, 2023). "YY1 also adjusts the levels of cytokines and growth factors (e.g., IL-6, IL-17, TGF-β, and IFN-γ), thereby modulating the therapeutic effect of tumor immune checkpoint drugs." (PMID 37408047, 2023). "Yin-yang-1 (YY1) is an important transcription factor regulating proliferation, migration and EMT of tumor cells." (PMID 37408047, 2023). "In Cox proportional hazards model, YY1 overexpression functioned as an independent prognostic factor after adjustment of hormone receptor/HER2 status and tumor size (hazard ratio of 0.50, 95% CI 0.26–0.98, p = 0.042)." (PMID 37444605, 2023). "Our findings corroborate previous reports by us and others, demonstrating the critical but opposite functions of YY1 and RKIP in the regulation of tumor sensitivities to drug and endogenous immune-mediated cytotoxic effects and/or immunotherapy." (PMID 37894300, 2023). "Comparison of the TAL and RMC populations from the treated tumour revealed a transcriptional switch from high HOXB9 and TFCP2L1 activity in TAL1 cells, to high MYC, HIF1A, YY1 and NFE2L2 activity in RMC cells." (PMID 37236926, 2023). "These examples demonstrate that YY1 overexpression leads to the maintenance of the CSC population, promotes tumor growth, and contributes to the resistance to therapy." (PMID 37444616, 2023). "Overall, these results indicate that a SIAH1–YBX-1-E2F5/YY1/RCC2 axis exists and that this axis plays an essential role in regulating the DDP sensitivity and tumor suppressor function of SIAH1." (PMID 35273154, 2022). "In summary, we describe a novel mechanism of ferroptosis in tumor cells based on the negative regulation exerted by YY2 on SLC7A11 transcription, and revealed a competitive, antagonistic regulation of YY1 and YY2 on the SLC7A11 promoter." (PMID 35246964, 2022). "Increasing evidences have demonstrated the tumor suppressive effect of YY2, in contrast with the oncogenic YY1; however, little is known about the biological and pathological functions of YY2." (PMID 35246964, 2022). "This computational analysis further indicates that YY1 plays as oncogene in LC, whereas RKIP as tumor suppressor." (PMID 35205667, 2022). "This study identified YY1 as an essential downstream effector of GRSF1 and rescued the tumor-inhibiting effect of GRSF1 knockdown, suggesting that GRSF1 promotes hepatocarcinogenesis by promoting YY1 expression." (PMID 34998399, 2022). "Exhaustion of tumor-infiltrating lymphocytes was mostly tied with overexpression of PD1, along with YY1-cofactor Ezh2." (PMID 35719931, 2022). "Immunohistochemistry assays showed that GRSF1, YY1 and Ki67 expression was decreased in the VE821 group tumor tissue (p<0.05)." (PMID 34998399, 2022).
tumor (continued). "Alterations in cell signaling modulate activities of transcription factors, such as NF-κB, YY1, and HIF-1/2, leading to enhanced expression of oncogenic miRNAs and/or decreased expression of tumor suppressing miRNAs." (PMID 36497298, 2022). "In NPC, YY1 mediates repression of TRIM26 and suppression of tumor growth by inactivating the transcriptional activity of c-Myc." (PMID 35408813, 2022). "Together with the affinities of YY1 and YY2 to SLC7A11 promoter, which also need to be elucidated, the change in YY1 and YY2 levels is crucial for the overall outcome of the ferroptosis level in tumor." (PMID 35246964, 2022). "YY1 showed the oncogenic role in CRC, especially playing the epigenetic regulative role on cancer stem cell transcription factors to accelerate tumor metastasis." (PMID 36262350, 2022). "qRT–PCR assays demonstrated that GRSF1, YY1 and Ki67 expression was decreased in the VE821 group xenograft tumor tissue, while miR-30e-5p expression was increased (p<0.01)." (PMID 34998399, 2022). "EGFR was positively upregulated by the epigenetic complex, p300/YY1, in a manner dependent on CRNDE expression, leading to enhanced tumor cell proliferation and sorafenib resistance." (PMID 35999564, 2022). "By selectively looking into the epithelial tumor cellular component and stratifying the hierarchical clusters based on the CMS, it was possible to observe a heterogeneous expression of both YY1 and BCL2L15." (PMID 34445183, 2021). "The transcription factors Ying Yang 1 (YY1) and CP2 have been shown to act as tumor suppressors and promoters." (PMID 33315124, 2021). "CRC single-cell sequencing dataset analyses demonstrated higher co-expression levels of both YY1 and BCL2L15 within defined tumor cell clusters." (PMID 34445183, 2021). "YY1 facilitates HCC cell lipid metabolism and tumor progression by inhibiting PGC-1β-induced fatty acid oxidation." (PMID 34335929, 2021). "Yin Yang 1 (YY1) is a transcription factor that is often overexpressed in cancers, and which is involved in the regulation of tumor cell growth, proliferation, migration, and metastasis." (PMID 34497757, 2021). "Some studies have shown that overexpression and binding of the transcription factor YY1 to the BRCA1 promoter inhibits the proliferation and focus formation of MDA-MB-231 cells and inhibits the growth of MDA-MB-231 tumor in nude mice." (PMID 34876062, 2021). "They found that the tumor suppressor YY1 bound to the promoter of SOX2OT and inhibited tumor growth in vivo and in vitro by suppressing SOX2OT and SOX2 expression in PC." (PMID 34760707, 2021). "MiR-500a-5p was confirmed to be a tumour suppressor that was significantly downregulated in CRC, inhibited CRC tumour growth and metastasis by regulating HDAC2 and was negatively regulated by YY1." (PMID 33865381, 2021). "YY1 represses the transcription of some of these death receptors, including death receptor 5 (DR5) and Fas in different tumor types." (PMID 34944867, 2021). "Inhibition of YY1 increases DR5 expression and in turn sensitizes tumor cells to TRAIL-mediated apoptosis." (PMID 32226547, 2020). "We also found that YY1 was a transcription factor for UPLA1 and inversely regulated UPLA1 as a tumour suppressor." (PMID 33221813, 2020). "Luo and collaborators evaluated YY1 (yin and yang 1) expression in ESCC and found it higher in tumours than in adjacent oesophagus and normal epithelium from healthy donors." (PMID 32429269, 2020). "Therefore, we found that YY1 could also act as a tumour suppressor in LUAD." (PMID 33221813, 2020).
tumor (continued). "YY1 protein was up-regulated in ESCC with lymph node invasion and its expression was more intense in late-stage tumours (III/IV) in comparison with early stage tumours (I/II)." (PMID 32429269, 2020). "In summary, we found that lncRNA UPLA1 was regulated by YY1 and promoted Wnt/β-catenin signalling by binding to DSP, thus leading to tumour progression in LUAD." (PMID 33221813, 2020). "YY1 was upregulated in HCC cells, and silenced YY1 restrained HCC cell proliferation in vitro and hampered tumor growth in vivo." (PMID 32943988, 2020). "Collectively, this evidence supports the notion that elevated YY1 expression contributes to the acquisition of an EMT phenotype and tumor metastasis." (PMID 32226547, 2020). "YY1/MAX expression in the tumor bulk and surrounding normal tissue was variable without any particular correspondence with the invasive subtype of the tumor." (PMID 33063251, 2020). "In this study, we found that YY1 promoted the expression of MZF1 in NB cells, resulting in facilitated glycolytic gene expression and tumor progression." (PMID 32042322, 2020). "YY1 gene knockout was also confirmed in isolated mouse lung ECs from YY1iΔEC mice and further confirmed with dual immunostaining of YY1 and EC specific CD31 marker in tumor tissue." (PMID 33235311, 2020). "This would indicate that O-GlcNAcylated YY1 will interact with AhR activation to increase the NAS/melatonin ratio, and thereby NAS trophic support for tumours." (PMID 33375613, 2020). "The data demonstrated that only USF1, YY1, STAT3 and USF2 were up-regulated in the three OS tumor samples when compared with paired normal specimens." (PMID 32269179, 2020). "Furthermore, YY1 could induce tumor angiogenesis in a HIF-1-independent manner." (PMID 32226547, 2020). "Further, they showed that YY1 and EZH2 mediate histone H3 lysine 27 trimethylation to silence several tumor suppressive miRNAs." (PMID 31824839, 2019). "On the other hand, YY1-dependent positive regulation of BRCA1 and HP1alpha results in tumor suppression and reduced invasiveness." (PMID 31824839, 2019). "NO is believed to dysregulate the NF-kB/SNAIL/YY1/RKIP/PTEN loop in tumor cells by repressing SNAIL, YY1, the prosurvival NF-kB pathway, and the anti-apoptotic AKT pathway." (PMID 31533363, 2019). "In all, we showed that LINC00673 is activated by YY1 and acts as a sponge for miR-515-5p, regulating MARK4, inactivating the Hippo signaling pathway, and resulting in tumor progression." (PMID 31623640, 2019). "YY1-dependent transcriptional activation and repression of ERBB2 and p27 respectively, leads to tumor promotion." (PMID 31824839, 2019). "YY1 was positively related to VEGFA, which are crucial to tumor angiogenesis, promote endothelial cell proliferation, and increase vascular permeability." (PMID 31799179, 2019). "Further analysis showed that YY1 expression was positively correlated with HDAC1 in HCC cell lines and tumor tissues." (PMID 28489564, 2017). "In this study, we found that YY1 expression exhibited a positive correlation with HDAC1 in cell lines and tumor tissues of HCC." (PMID 28489564, 2017). "Its overexpression can also induce tumor cell sensitivity to TRAIL apoptosis, perhaps due to consequential inhibition of YY1 and upregulation of DR5." (PMID 28476134, 2017). "We demonstrated that miR-361 is a tumor suppressor in EC, and EZH2 binds directly to the miR-361 promoter to suppress its transcription through a YY1-dependent manner." (PMID 28088786, 2017). "We also indicated that YY1 was positively correlated with HDAC1 in HCC cell lines and tumor tissues, while there was a reciprocal regulation between YY1 and HDAC1." (PMID 28489564, 2017). "Stable over-expression of YY1 led to increased in vivo growth of SGC-7901 cells in athymic nude mice and enhanced tumor weight of established subcutaneous xenograft tumors." (PMID 28827574, 2017).
tumor (continued). "We now demonstrate that oncogenic MCT-1 activation elevates ROS generation and amplifies YY1-EGFR-MnSOD signaling, accompanied by tumor promotion and a malignant microenvironment." (PMID 28394354, 2017). "Here we found for the first time that in contrast to YY1, which had been reported to be oncogenic, the expression level of YY2 in tumor cells and/or tissues was downregulated compared with its expression level in the normal ones." (PMID 28903375, 2017). "In this study, firstly, we identified two drug-response profiles to HDACi in HCC cell lines, while our results showed that HDAC1 expression was positively correlated with YY1 in HCC cell lines and primary tumor tissues." (PMID 28489564, 2017). "Previous reports showed that full-length HBx can transcriptionally suppress a subset of important tumor-related genes through enhancing the promoters binding to transcription suppressors like E2F1, SMAD4, YY1 and MAZ." (PMID 27391153, 2016). "Furthermore, although molecular links between Notch1 and NF-κB during tumor progression and metastasis have been suggested by the previous work, a mechanism of disrupting or directly regulating Notch1 signaling from within the NF-kB/Snail/YY1/RKIP loop was unclear." (PMID 26716415, 2016). "In contrast, PDT-induced high levels of NO result in the inhibition of NF-kB, Snail, and YY1 and the induction of RKIP, all of which result in significant anti-tumor cytotoxicity." (PMID 26319434, 2015). "We have identified Yin Yang 1 (YY1), a dysregulated transcription factor, whose overexpression correlated with tumor progression as well as in the regulation of drug resistance and the development of EMT." (PMID 25053986, 2014). "Although the post-transcriptional interplay between YY1 and c-MYC and between YY1 and HDAC2 both favour tumour progression, the former activates the fast cell cycle/pluripotency genes, and the latter represses differentiation/fast cell cycle inhibitor genes." (PMID 25115389, 2014). "Clearly, overexpression of YY1 has been noted in many cancers and was shown to play a pivotal role in the regulation of EMT and metastasis as well as its role in the regulation in tumor cell resistance to both chemotherapy and immunotherapy." (PMID 25053986, 2014). "By contrast, YY1 expression was elevated in PCa tumors as compared with that in PIN, and was increased with higher tumor grade." (PMID 25174820, 2014). "YY1 expression was barely detectable in PIN tissues and was significantly increased (P<0.001, ANOVA) with an increase in tumor grade." (PMID 25174820, 2014). "The sensitization of tumor cells to CDDP by DETANONOate was the result, in part, in the inhibition of NF-κB, YY1 and anti-apoptotic gene products such as Bcl-2 and Bcl-xl." (PMID 25053986, 2014). "The C3TFT gene-sets that were more highlyexpressed in the tumour tissue had common regulatory motives for various E2Fs, NRF2, ARNT, NRF1, MYC and YY1." (PMID 23009663, 2012). "Bioinformatic analysis of mRNA targets of the altered miRNAs, identified oncogenes like ERBB2, YY1, several MAP kinases, and known tumor-suppressors like FOXA1 and SMAD4." (PMID 22438871, 2012). "Through various layers of regulation, YY1 modulates PD-L1 to contribute to a more immunosuppressive tumor microenvironment unlike RKIP." (PMID 41327312, 2025). "The results showed that the group with YY1 knockdown combined with anti‐PD‐1 treatment exhibited significant tumor growth inhibition, whereas the GALNT16 overexpression group showed accelerated tumor growth." (PMID 41322030, 2025). "Targeting the MAGEA6/YY1/CXCL1‐SC axis may provide a promising strategy to inhibit PNI and tumor progression, ultimately improving patient prognosis." (PMID 40145793, 2025). "YY1-induced PLK1 expression elevates G6PD levels, activating the pentose phosphate pathway and increasing NADPH and glutathione (GSH) production, thereby driving tumor cells’ resistance to paclitaxel and cisplatin." (PMID 40867514, 2025).
tumor (continued). "Meanwhile, studies have shown that YY1 can also slow down the transcriptional activation of IFN-γ by activating the JAK-STAT pathway and forming a protein complex with the nuclear factor AP2, thereby accelerating tumor invasion." (PMID 40704062, 2025). "Concurrently, YY1 promotes EMT, enhancing tumor cell invasion and migration." (PMID 40145793, 2025). "Within the NF-κB/Snail/YY1/RKIP loop, hyperactivation of NF-κB promotes YY1 and Snail while suppressing RKIP and creates a self-reinforcing circuit that maintains a resistant and invasive tumor phenotype." (PMID 41327312, 2025). "Additionally, YY1 upregulates CD47 expression, inhibiting macrophage phagocytosis, facilitating tumor cell immune escape, and contributing to treatment resistance." (PMID 40867514, 2025). "Testing all variables for YY1 quantification by receiver operating characteristic (ROC) curves, we found potential prognostic factors among those within the tumor areas but not in the whole spots (tumor + normal) (respectively)." (PMID 41009346, 2025). "This level of spatial resolution is critical given that YY1 is also expressed in non-tumor cells within the tumor microenvironment, including infiltrating lymphocytes and fibroblasts." (PMID 41009346, 2025). "Conversely, YY1 may enhance JNK signaling through Smail induction, further contributing to immune dysregulation and tumor immune escape." (PMID 41459495, 2025). "Treatment with tunicamycin alone significantly inhibited PD‐L1 expression in tumor cells, and this inhibitory effect was independent of YY1 expression levels, indicating that glycosylation indeed enhanced the stability of PD‐L1." (PMID 41322030, 2025). "MAGEA6 interacts with the transcription factor Yin‐Yang 1 (YY1), which subsequently increases the secretion of CXCL1 by CRC cells, facilitates the recruitment of CRC cells to SCs, while also enhancing tumor cell invasiveness through epithelial‐mesenchymal transition (EMT), ultimately promoting PNI." (PMID 40145793, 2025). "YY1 directly transcriptionally activates PD-L1, LAG-3, and TIM3 transcription, which induce T cell exhaustion across various cancer types while enhancing tumor resistance to cisplatin and other chemotherapeutic agents." (PMID 40867514, 2025). "As a nitric oxide donor, DETA-NONOate can inhibit YY1 through S-nitrosylation, thereby inhibiting its DNA binding ability and sensitizing tumor cells to Fas-induced apoptosis." (PMID 41327312, 2025). "Consequently, YY1/HIF-1a upregulates VEGF expression and drives tumor vascularization to augment oxygen and nutrient perfusion." (PMID 40867514, 2025). "Various agents were described to inhibit YY1 and restore RKIP expression, including small molecules, peptides, RNA-based therapeutics, and gene editing tools that re-sensitize tumors to immunotherapy, and suppress tumor-promoting signaling pathways." (PMID 41327312, 2025). "YY1 recruits BETs (including BRD2, BRD4) to bind to cis-regulatory elements of transcription factor 7 like 2 (TCF7L2), thereby regulating the expression of TCF7L2, cooperatively activating tumor cell DNA repair capacity and driving therapeutic resistance." (PMID 40867514, 2025). "However, IL-18 (a pro-inflammatory cytokine) suppresses FXR activity while simultaneously activating the NF-κB/YY1 axis, contributing to the downregulation of MRP2 expression, therefore promoting cancer cells’ chemoresistance under the tumor microenvironment." (PMID 40867514, 2025).